CHST15 (carbohydrate sulfotransferase 15)
Description:
Sulfotransferase that transfers sulfate from 3'-phosphoadenosine 5'-phosphosulfate (PAPS) to the C-6 hydroxyl group of the GalNAc 4-sulfate residue of chondroitin sulfate A and forms chondroitin sulfate E containing GlcA-GalNAc(4,6-SO(4)) repeating units. It also transfers sulfate to a unique non-reducing terminal sequence, GalNAc(4SO4)-GlcA(2SO4)-GalNAc(6SO4), to yield a highly sulfated structure similar to the structure found in thrombomodulin chondroitin sulfate. May also act as a B-cell receptor involved in BCR ligation-mediated early activation that mediate regulatory signals key to B-cell development and/or regulation of B-cell-specific RAG expression; however such results are unclear in vivo.
Synonyms: GalNAc4S-6ST; BRAG; KIAA0598
Tractability: Antibody: UniProt predicts a signal peptide or a membrane-spanning region. PROTAC: ubiquitination databases record sites on it.
Gene: Protein-coding gene on chromosome 10 (124,007,668 to 124,093,698, reverse strand). Ensembl gene ENSG00000182022.
Subcellular location: Golgi apparatus membrane
Subcellular location (Human Protein Atlas): Cytosol; Centrosome
Pathways (Reactome):
Metabolism: CS-GAG biosynthesis; DS-GAG biosynthesis
Gene Ontology:
Molecular function: 3'-phosphoadenosine 5'-phosphosulfate binding; N-acetylgalactosamine 4-sulfate 6-O-sulfotransferase activity; protein binding; sulfotransferase activity
Biological process: hexose biosynthetic process; chondroitin sulfate proteoglycan biosynthetic process; dermatan sulfate proteoglycan biosynthetic process
Cellular component: Golgi membrane; membrane
Genetic constraint (gnomAD): Loss-of-function variants: 30 observed, 54.75 expected, observed/expected ratio (o/e) 0.55, 90% interval 0.41 to 0.74. The upper end of that interval is the gene's LOEUF score, 0.74, which puts it in group 3 of 6, group 1 being the genes least tolerant of losing a copy. Missense variants: 627 observed, 768.19 expected, observed/expected ratio (o/e) 0.82, 90% interval 0.76 to 0.87. Synonymous variants: 296 observed, 300.05 expected, observed/expected ratio (o/e) 0.99, 90% interval 0.9 to 1.09.
Homologues: Orthologues: chimpanzee CHST15 (99% identical), macaque CHST15 (99% identical), mouse Chst15 (93% identical), rat Chst15 (93% identical), guinea pig CHST15 (92% identical), pig CHST15 (89% identical), rabbit CHST15 (88% identical), zebrafish chst15 (52% identical), tropical clawed frog chst15 (48% identical).